CXCR4 (C-X-C motif chemokine receptor 4)
Diseases named in the same sentence as CXCR4 in open-access papers (continued):
Sharing a sentence is not in itself a finding about the gene and the disease.
cancer (continued). "Moreover, blocking agents and antibodies directed against CXCR4 prevent metastasis of different cancers in the preclinical setting." (PMID 22811589, 2012). "It is also recognized that metastastic behaviour of cancer cells may be reinforced by hypoxia, a condition that induce up-regulation of CXCR4 expression mediated by hypoxia-inducible factor-1a (HIF-1α)." (PMID 22417013, 2012). "We found that CD133+CXCR4+ cancer cells had a high metastatic capacity in vitro and in vivo." (PMID 22871210, 2012). "Finally, we analysed the expression pattern of Cxcr4 because of its known expression in numerous normal as well as cancer stem cell populations and its proposed role in cell migration and metastatic infiltration." (PMID 22349813, 2012). "A more complete understanding of CXCL12/CXCR4 signaling pathways may support efforts to develop therapeutics for cancer." (PMID 23202899, 2012). "The expression of CXCR4 was also detected in CD133+ cancer cells." (PMID 22634835, 2012). "The intended outcome of current work was the development of a unique small molecule that will effectively attenuate cancer metastasis in vivo by blocking CXCR4 function whilst demonstrating a specificity profile to merit advancement into human clinical evaluation." (PMID 22485156, 2012). "The finding that both hybrid cells were positive for CXCR4 may suggest that cell fusion might be a mechanism how (breast) cancer cells could acquire the ability to metastasise in an organ-specific manner." (PMID 22487193, 2012). "Interestingly, the expression of CXCR4 within the cancer cells was shown to also be induced by NF-κB." (PMID 23342263, 2012). "SDF-1α in pre-metastatic niche may capture circulating CXCR4+ cancer cells and then provide one pathway for metastasis formation." (PMID 23300882, 2012). "Our findings suggest preferential Treg recruitment in basal-like cancers may be in part explained by CXCR4 up-regulation in Treg." (PMID 21521526, 2011). "In conclusion, our results provide evidence that CXCR4 is up-regulated in CRC and stimulation of CXCR4 bearing cancer cells with CXCL12 led to increased migration, an effect which could be inhibited both by CXCR4 siRNA and neutralizing CXCR4 antibodies." (PMID 21349176, 2011). "Moreover, upregulation of CXCR4 has frequently been observed in various cancers, including colon carcinoma, lymphoma, breast cancer, glioblastoma, leukemia, prostate cancer, oral squamous cell carcinoma and pancreatic cancer." (PMID 21912642, 2011). "Thus, novel agents that can downregulate the CXCR4/CXCL12 axis have therapeutic potential in inhibiting cancer metastasis." (PMID 21880153, 2011). "Events triggered by CXCL12 may play a part, as CXCL12 drives the migration of both CXCR4-positive cancer cells and macrophages and may promote a molecular crosstalk between them." (PMID 20946648, 2010). "Thus, understanding the mechanisms that normally regulate CXCR4 expression and function should prove useful in the treatment and prevention of cancer metastasis." (PMID 21110890, 2010). "Moreover, these authors provided evidence that Src enhanced the survival of the metastatic cancer cell line by mediating the activation of PKB/Akt in response to CXCR4 activation." (PMID 20152043, 2010). "All the data previously discussed provide the rationale for targeting CXCR4 in cancer." (PMID 20049170, 2010). "Consequently, there is a great deal of interest in developing anti-cancer therapeutics targeting CXCR4." (PMID 20502531, 2010). "Moreover, the study demonstrated that tumor metastasis depended on a subpopulation of migrating CD133+CXCR4+ cancer stem cells." (PMID 24281171, 2010). "Subsequent studies have demonstrated CXCR4 expression in a variety of cancer cells and tumors." (PMID 20849618, 2010). "Additionally, it is important to further establish the mechanisms that result in increased CXCR4 expression andpotentially target such pathways in cancer treatment." (PMID 21110890, 2010).
cancer (continued). "In contrast, functional CXCR4 is widely expressed by different types of cancer cells." (PMID 20569497, 2010). "Cancer cells stained positive for CXCR4, CXCL12, HER1, HER4 and GM-CSF." (PMID 20946648, 2010). "The activation of the SDF-1-CXCR4 signaling pathway may promote the migration and adhesion of CXCR4+ disseminated cancer cells to endothelial and stromal ECM components at the distant metastatic sites." (PMID 24281178, 2010). "Overexpression of CXCR4 has been reported in a variety of tumors, primarily carcinoma." (PMID 20102637, 2010). "Importantly, endogenous CXCR4 expression on carcinoma cells is known to correlate with a poor prognosis for several types of carcinomas." (PMID 20569497, 2010). "Furthermore, our data suggest a role of the chemokine CCL20 in CXCR4-dependent and independent regulation of cancer growth and point to CCR6 and CCL20 as novel therapeutic targets in cancer." (PMID 19340288, 2009). "Altogether, our findings for the first time provide evidence for existence of a putative CXCR4/CCL20 interaction that could be involved in cancer development processes." (PMID 19340288, 2009). "Thus, CXCL12 ligand-induced activation of CXCR4 on malignant cancer cell lines and peripheral blood mononuclear cells triggered down-regulation of MHC class I from the cell surface." (PMID 19119421, 2009). "Other surface markers such as CXCR4 and ABCG2 may be associated with cancer stem cell characteristics." (PMID 20027313, 2009). "CXCR4 has been the major chemokine receptor expressed on cancer cells." (PMID 19563666, 2009). "Additionally, CXCR4 and its specific ligand SDF-1 were shown to be associated with several cancers, such as breast cancer, head and neck cancer, small-cell lung cancer and non-small-cell lung cancer." (PMID 19223978, 2009). "Altogether, our findings provide evidence for the existence of a putative CXCR4/CCL20 interaction that could be involved in cancer development processes." (PMID 19340288, 2009). "CXCR4 staining showed a predominantly cytoplasmic distribution in the cancer cells." (PMID 19352387, 2009). "One emerging candidate for targeted therapy in cancer and several other diseases is CXCR4." (PMID 20028517, 2009). "The reasons for this observation may be due to our limited sample size since the pool of circulating CXCR4 positive cells may represent cancer stem cells and comprise a smaller proportion of the cells." (PMID 19563666, 2009). "We suggest that TZD therapy, bystimulating PPARγ-dependent downregulation of CXCR4 on cancer cells, may slowthe rate of metastasis and may impact beneficially on disease progression." (PMID 18779872, 2008). "Furthermore, metastasis of cancer cells to regional lymph nodes and lung in immunodeficient mice were inhibited by a neutralizing antibody against CXCR4." (PMID 18826577, 2008). "All seven Gli-1 nuclear-positive cancers expressed CXCR4, COX-2, and VEGF." (PMID 18475300, 2008). "Adjuvant therapy using PPARγ agonists may, bystimulating PPARγ-dependent downregulation of CXCR4 on cancer cells, slow the rate of metastasis and impact beneficially ondisease progression." (PMID 18779872, 2008). "With the inhibition of CXCR4, the growth and invasion could be impaired in some type of cancer cells." (PMID 19002187, 2008). "This population might be responsible for cancer resurgence and could also begin to device translational studies with combinations of available CXCR4 and Tac1 peptide receptor antagonists." (PMID 18575622, 2008). "Because CXCR4 enhances cancer invasiveness by matrix metalloprotease-13, which is important for invasion of cancer cells by degrading extracellular matrix, this data may support our results of enhanced-invasiveness via NO-CXCR4 signaling." (PMID 19025611, 2008). "It is similar to previous reports and also suggests that CXCR4 may be a useful marker for cancer progression." (PMID 19002187, 2008). "Cytoplasmic and nuclear CXCR4 expression in cancer cells has been described in various cancers." (PMID 19025611, 2008).
cancer (continued). "Elevated CXCR4 expression was correlated to an advanced cancer stage and metastasis." (PMID 19002187, 2008). "Recent studies indicate that CXCR4 is one of the critical factors for metastasis homing on specific organ sites in that SDF-1 released in target organs may attract nearby or distant CXCR4-expressing cancer cells." (PMID 19116653, 2008). "Therefore, CXCR4-expressing cancer cells arecertainly attracted to the typical “homing organs” such as lungs, bone marrow,liver, and lymph-nodes showing a high SDF-1α expression." (PMID 19266088, 2008). "Antagonists of CXCR4 such as the T140 analogs might be useful lead compounds for the development of anti-metastatic agents in several types of cancer." (PMID 19787093, 2008). "Thus, we suggest that HDAC inhibitors are involved indirectly in Met and CXCR4 induction by controlling the activities of transcription factors with different mechanisms that possibly depended on carcinoma cell aggressiveness." (PMID 18941460, 2008). "Also, previous reports established that CXCR4 was up-regulated by hypoxia in monocytes, endothelial cells, and cancer cells by the stabilization and activation of HIF-1α protein." (PMID 17476338, 2007). "Hence, targeting non-redundant signalling axes like TGFβ and CXCR4 is necessitated as they affect progression of metastasis, facilitate epithelial-mesenchymal transition and are implicated in maintenance of cancer stem cells." (PMID 41348904, 2025). "Therefore, the optimization of existing scaffolds or the discovery of new ones, based on SAR studies, may pave the way for new CXCR4 antagonists useful in tackling multiple types of cancer." (PMID 40142155, 2025). "Furthermore, cancer cells may adopt alternative survival pathways or phenotypes that bypass CXCR4 inhibition." (PMID 41002447, 2025). "Interestingly, the diverse CXCR4 location may activate different signaling pathways, cellular responses, and cancer progression." (PMID 38893721, 2024). "Moreover, markers of cancer stem cells, ALDH1 and CXCR4, are strongly associated with GHR in PDAC." (PMID 39000545, 2024). "Therefore, the CXCR4/CXCL12 axis seems to be a promising target for cancer therapies." (PMID 39457017, 2024). "Data from cancer studies may support JunB modulation of CXCR4 in other cell types." (PMID 38835488, 2024). "In addition, Zhou and colleagues found that E26 transformation-specific homologous factor could decrease the sensitivity of PDAC cells to niche stimulus of cancer stem cells by inhibiting the transcription of CXCR4." (PMID 38167055, 2024). "Therefore, CXCR4 becomes an important therapeutic target in the treatment of cancer." (PMID 38397018, 2024). "Moreover, our findings on the modulation of metastatic markers such as uPAR, uPA, CXCR4, MT1-MMP, and TNF-α by PEDF, Dox, and their combinations add critical insights into the molecular mechanisms underlying cancer progression and confirmed the results from migration." (PMID 38474001, 2024). "Therefore, it is possible that advanced HIV infection drives CXCR-4 overexpression in cancer cells." (PMID 39001265, 2024). "Using a highly sensitive and specific assay like PLA, our study is the first that uses cancer cells endogenously expressing CXCR4 and β2AR to demonstrate that the two receptors may form heteromers or are at least in close enough proximity that allows receptor crosstalk." (PMID 37878624, 2023). "CXCL12 promotes cancer development by two main mechanisms: i) directly activating signaling pathways involved in cancer cell growth, metastasis, and angiogenesis, and ii) indirectly promoting metastasis by recruitment of CXCR4+ cancer cells to CXCL12-expressing organs." (PMID 37251376, 2023). "Therefore, CXCR4 is considered a potential therapeutic target for cancer treatment." (PMID 37538932, 2023). "Thus, CXCR4 is regarded as a promising therapeutic target for the treatment of cancer." (PMID 37749552, 2023).
cancer (continued). "Interestingly, several interacting proteins were also implicated in cancer progression, suggesting that the protein–protein interaction network involving CXCR4 may be relevant to cancer biology." (PMID 36992255, 2023). "ob-aT bASCs exhibited an increased ability to stimulate cancer stemness in highly malignant MDA-MB-231 cells by enhancing the gene expression of pluripotency and CSC associated genes such as ALDH1H1, ALDH2, c-MYC, CD34, LGR5, CXCR4, SOX2 and OCT4, fueling further their malignant potential." (PMID 36710348, 2023). "Moreover, the CXCL12/CXCR4/7 axis could also facilitate cancer cells proliferation and survival through ERK, AKT, and Ras signaling pathways." (PMID 36612163, 2022). "Therefore, CXCR4 serves as an important therapeutic target for treating cancers and HIV infection." (PMID 35359589, 2022). "Thus, in recent decades, CXCR4 has been exploited as a molecular target for cancer treatment." (PMID 35456719, 2022). "Furthermore, CXCR4 is involved in tumorigenesis and progression in many cancers, especially PC." (PMID 36145541, 2022). "Furthermore, NF-κB could activate CXCR4 expression through binding to the CXCR4 promoter, subsequently leading to increased migration and metastasis of cancer cells." (PMID 36290780, 2022). "Therefore, understanding the regulatory mechanisms of CXCR4 in cancer cells is of great importance." (PMID 36054080, 2022). "However, to date, the study of the effect of CXCR4 overexpression on metastatic dissemination in EC mouse models has not been addressed yet, whereas in a majority of evaluated cancers, CXCR4 overexpression is associated with a worse prognosis." (PMID 35884987, 2022). "Furthermore, it is possible that Treg recruitment by CXCR4 in these cancers could be modulated by treatment directed against hypoxia pathway factors, including HIF-1α." (PMID 35358193, 2022). "The inhibition of CXCR4 using continuous infusion of the small-molecule inhibitor AMD3100 (plerixafor) relieved this suppression, resulting in enhanced T and NK cell infiltration with a concomitant decrease in the recruitment of cancer-associated fibroblasts (CAF)." (PMID 35205725, 2022). "Moreover, both of the cell lines were characterized by lower expression of claudin-2 (CLDN2), C-X-C chemokine receptor type 4 (CXCR4), and cytochrome P450 family 24 subfamily A member 1 (CYP24A1), which codify for proteins commonly reported to be associated with cancer progression and invasiveness." (PMID 35159043, 2022). "In particular, we show that the anti-cancer action triggered by metformin relies on its ability to inhibit the insulin/IR-mediated transduction pathway as well as the insulin-generated feedforward loop that couples CXCL12 induction by CAFs to CXCR4 expression by BCAHC‐1 cells." (PMID 35672854, 2022). "However, the role of CXCR4 expression in cancer metastasis is still controversial." (PMID 35877436, 2022). "Moreover, CXCL12 activating CXCR4 promotes the transfer of proto-cancer mitochondria between cells." (PMID 35630915, 2022). "CXCR4 is a 7-transmembrane G-protein coupled receptor and highly expressed in a variety of cell types, including lymphocytes, endothelial, epithelial and hematopoietic stem cells, stromal fibroblasts and cancer cells and plays a major role in embryogenesis, homeostasis and inflammation." (PMID 35397601, 2022). "Thus, T22-DITOX-H6’s ability to eliminate CXCR4+ cancer cells presenting a more invasive and metastatic phenotype blocks HNSCC’s invasiveness and its metastatic dissemination to the cervical lymph nodes, lungs, and liver, in the absence of histopathological alterations." (PMID 35456719, 2022). "Therefore, this dynamic expression profile could enhance the role of JUNB and CXCR4 in invasion, establishment of cancer cells in a new tissue and metastasis, confirming related studies." (PMID 36612166, 2022).
cancer (continued). "CXCL12 acts primarily via two mechanisms in cancer: (a) through an autocrine effect that promotes cancer cell growth, invasion, and angiogenesis, and (b) indirectly by recruiting cancer cells expressing CXCR4 into regions or organs containing CXCL12 to initiate metastasis." (PMID 35745762, 2022). "Moreover, cancer cells of the luminal BC communicate with immune cells through CXCL12_CXCR4." (PMID 36077333, 2022). "Moreover, activating CXCR4 could contribute to resistance of cancer cells to signal transduction inhibitor and chemotherapy-induced apoptosis." (PMID 34077304, 2021). "In addition, TAMs also utilize CCR5 and CXCR4 for their recruitment in some types of cancer." (PMID 34885241, 2021). "Thus, CXCR4 inhibitors may also provide a promising approach for suppression of MDSCs in cancer immunotherapy." (PMID 34885241, 2021). "Furthermore, the CXCL12/CXCR4 axis is involved in cancer cell intravasation." (PMID 33530455, 2021). "Importantly, multiple studies have reported that CXCL12/CXCR-4 axis activation enhances cancer cell adhesion, migration, and invasion, leading to increased metastasis, and specific blockage via neutralizing antibodies targeting CXCR4 can partly interrupt this process." (PMID 34069563, 2021). "Further, some reports have suggested that the in vivo environment gives cues to the cancer cells to transport their intracellular CXCR4 on the surface, so to test the same, we isolated single cells from harvested in vivo xenograft tumors and examined the CXCR4 surface expression." (PMID 33966046, 2021). "Thus, dual CXCR4/CXCR7 inhibition will target different cancer components." (PMID 33937018, 2021). "Aberrant cancer signaling may result in CXCR4 overexpression." (PMID 34298991, 2021). "In addition, pDCs-derived TNF-α in breast tumors triggered activation of the NF-κB signaling pathway in cancer cells, which in turn upregulated the expression level of CXCR4 and led to increased metastasis to lymph nodes, which ultimately promoted cancer progression." (PMID 34737750, 2021). "Therefore, selective inhibition of CD90+ and CXCR4+ cells, resulting in reduced cancer metastasis, may provide significant improvements in the current therapeutic approaches in HCC patients." (PMID 34456716, 2021). "Therefore, after briefly summarizing the current clinical status quo of CXCR4-targeted theranostics in cancer, this review primarily focuses on imaging of a broad spectrum of inflammatory diseases via the quantification of tissue infiltration with CXCR4-expressing immune cells." (PMID 34885030, 2021). "Therefore, we investigated the role of human NANOG in CXCR4-mediated cancer cell migration." (PMID 34638956, 2021). "Extending these data to clinical practice suggests that modulating the TME by targeting the IL-33/CXCR4 signaling circuit may attenuate the aggressiveness of cancer cells and provide a novel therapeutic strategy in precision medicine to improve the prognosis in HNSCC patients." (PMID 34298657, 2021). "Therefore, CXCR4 might be a latent biomarker in GC, which determines the efficacy of cancer immunotherapy." (PMID 34568309, 2021). "Although the molecular mechanisms underlying cancer metastasis remain to be fully elucidated, accumulating evidence points on a significant role of CXCL12/CXCR4 in the process, suggesting that the CXCL12/CXCR4 axis may be a potential therapeutic target in BC." (PMID 32228629, 2020). "However, the chemokines and their receptors that particularly stimulate tumorigenesis, including CCR7, CXCL1, CXCL8, and CXCL12/CXCR4, could, consequently, act as poor prognostic markers for cancer patients." (PMID 31991604, 2020). "Similarly, CXCR4+ cancer cells are metastatic stem cells in several solid tumors." (PMID 32295630, 2020). "Therefore, cancer treatment by targeting CXCR4 signaling pathways should be beneficial." (PMID 33392074, 2020).